STAT2 (signal transducer and activator of transcription 2)
Diseases named in the same sentence as STAT2 in open-access papers (continued):
Sharing a sentence is not in itself a finding about the gene and the disease.
viral infection (continued). "Phosphorylated STAT1 and STAT2 then bind with IRF9 to form a complex called IFN-stimulated gene factor 3 (ISGF3) to initiate the transcription of hundreds of genes that act to block viral infection." (PMID 30840887, 2019). "Interestingly, AXL is associated with viral infection, TLR7/8 transcript abundance, and STAT2 transcript abundance in placenta cells, since their levels vary both when these cells are infected as well as when TLR7/8 or STAT2 are knocked down." (PMID 30453684, 2018). "In addition to STAT1 and STAT2, the other STATs activated by type I IFNs can be inhibited by virus infection, which has been less investigated; the role of other STATs in the IFN-mediated response still requires further investigation." (PMID 29312301, 2017). "The one observed case of severe disseminated infection leading to death occurred after an unknown viral infection in an infant, suggesting that STAT2 may play an essential but narrow role in early childhood." (PMID 27190218, 2016). "IFNα is involved in the innate immune response against viral infections and our results therefore suggest that RV infection may activate STAT2 through the IFNα signaling pathway." (PMID 25874939, 2015). "However, the adaptive immune response to the virus infection seems to be intact with the STAT2 KO hamsters, and surviving animals clear the virus effectively." (PMID 26291525, 2015). "In addition, it is conceivable that IRF9-inhibition by the immediate early gene ORF63 precedes STAT2 inhibition due to sequential expression of the respective inhibitory proteins during viral infection." (PMID 25973608, 2015). "The initial purpose of engineering mutations within the elongin C biding domain of NS1 was to investigate if NS1 did form an E3 ligase complex to degrade STAT2 in a live virus infection, and to alter this function, such that STAT2 degradation was reduced during RSV infection." (PMID 21600055, 2011). "It has been previously shown that mice completely lacking STAT2 were extremely susceptible to viral infections." (PMID 19272190, 2009). "Nonetheless, susceptibility of the mutant mice to viral infections also indicates that the residual STAT2 is not sufficient to mount an antiviral response and there is a threshold requirement of STAT2 for type I IFNs to be fully functional." (PMID 19272190, 2009). "This situation can readily be observed in deficiencies of STAT2, TYK2, IFNAR1, and IFNAR2, in which severe viral disease affects some but not all individuals, with a greater penetrance observed for infections with live-attenuated viral vaccines than for common viral infections of childhood." (PMID 41608500, 2025). "Moreover, molecular compounds that antagonize the interaction between viral proteins such as NSm and host factors such as STAT2 may be used to treat viral infections." (PMID 41187197, 2025). "In contrast, patients with complete AR STAT2 deficiency typically present with disseminated infection from live attenuated vaccines and recurrent viral infections, with incomplete penetrance, since STAT2 does not participate in signaling upon engagement of the IFNGR." (PMID 37047709, 2023). "Notably, co-IP analysis provided meaningful information that OPRP2 highly induced type I IFN-dependent signaling pathways via STAT1/STAT2 heterodimerization that consequently activated powerful cellular responses to extraneous attacks such as a viral infection." (PMID 35740960, 2022). "Therefore, other STAT2-independent pathways may be induced by the viral infection, illustrating the robustness and redundancy of the innate antiviral defenses in fish." (PMID 31142600, 2019). "STAT2 deficiency in both patients and animals accordingly precludes the up-regulation of hundreds of genes in response to IFN-α or IFN-β and the other type 1/3 IFNs, many of which have direct and indirect antiviral activity, and results in a marked susceptibility to viral infections." (PMID 27780205, 2016).
viral infection (continued). "Similarly, STAT2-deficient mice exhibit reduced responsiveness to type I IFN and are more susceptible to viral infection, whereas STAT1-deficient mice are defective in their response to both type I and II IFNs and are highly sensitive to both viral and intracellular bacterial infections." (PMID 21379341, 2011). "Moreover, MEFs derived from P117 mice and the mice were extremely susceptible to viral infections, suggesting that the remaining STAT2 was not sufficient to confer antiviral response." (PMID 19272190, 2009). "Signal transducer and activator of transcription 2 (STAT2) is a key component of the type I interferon (IFN-I/III) signaling pathway, which is pivotal in host defense against cancer and viral infections and in shaping immune responses." (PMID 41907187, 2026). "One day before infection, IFNAR antibody, an IFN-A receptor antagonist, was administered to enable efficient viral infection, as ZIKV NS5 protein cannot effectively inhibit STAT2 in mice." (PMID 40688087, 2025). "STAT2 is involved in type I and type III interferon signaling, which are important for the immune response against viral infection." (PMID 41157650, 2025). "Consequently, biallelic LOF mutations in STAT2 impair the formation of the ISGF3 complex, disrupting the induction of interferon-stimulated antiviral genes (ISGs), resulting in defective IFN-α and IFN-β signaling and an inadequate ability to control viral infections." (PMID 41438753, 2025). "STAT2 is critical in the body’s defense by activating the type I interferon (IFN) pathway, which can restrict tumor growth and viral infections." (PMID 41440237, 2025). "Viral infections interact mainly with the activated Signal Transducer and Activators of Transcription 1, 2, and 3 (STAT1, STAT2 and STAT3) to release pro-inflammatory cytokines to eliminate viruses." (PMID 38628843, 2024). "To assess the effect of mSTAT in the viral infection context, we transfected HEK-293T cells with WT STAT1/STAT2 or its mutants for 24 h, followed by SVA infection for 12 h." (PMID 38869319, 2024). "During viral infection, IFN-1 cytokine binding to its respective IFN receptor (IFNAR1/2) triggers STAT1 and STAT2 phosphorylation and heterodimerization." (PMID 35572196, 2022). "Recent studies revealed that unphosphorylated STAT2 (U-STAT2), IRF9, and U-STAT1 can form unphosphorylated ISGF3, which can prolong and sustain resistance to virus infection and DNA damage." (PMID 36357830, 2022). "Knockdown of NLRX1 leads to enhanced transcription levels of IFNb1, STAT2, and the 2′-5′-oligoadenylate synthetase 1 gene (OAS1) after viral infection, suggesting a negative regulatory role of NLRX1 on the IFN-β/STAT2/OAS1 axis." (PMID 33525590, 2021). "During the onset of viral infection, the type 1 interferon (IFN1) and cytokines are promptly induced against the viral infection, whereas 3Cpro is involved in the inhibition of IFN-α/β by blocking the nuclear translocation of STAT1/STAT2." (PMID 33255534, 2020). "Signal transducer and activator of transcription 2 (STAT2) is critical for type I and type III IFN signaling and plays an important role in host defense responses against viral infections." (PMID 31921042, 2019). "During viral infection, type I IFN signaling through IFNAR induces STAT1/STAT2 activity, but also leads to the induction of STAT3, which is thought to provide negative feedback keeping the IFN response under control." (PMID 30473701, 2018). "During virus infection C6 reduces ISRE-dependent gene expression despite the presence of the viral protein phosphatase VH1 that dephosphorylates STAT1 and STAT2." (PMID 27907166, 2016). "IRF3 and IRF7 have been implicated as positive regulators of IFN-I gene expression induced by virus infections, whereas IRF9 constitutes an IFN-stimulated gene factor 3 together with STAT1 and STAT2, and is responsible for the induction of the IRF7 gene." (PMID 24903089, 2014).
viral infection (continued). "IE1 is not essential for viral replication, but enhances replication by targeting intrinsic barriers to viral infection (PML-bodies, hDaxx, STAT-2, and p107), whereas IE2 is essential and is a potent transcriptional transactivator." (PMID 24787765, 2014). "Human STAT2 deficiency can lead to the absence of STAT2-dependent types I and III IFN immunity, resulting in defects in antiviral immunity and a predisposition to severe viral infections." (PMID 39339845, 2024). "Next, we studied in detail the host-induced reaction to viral infection on a transcriptomic level, seeing that iPNs have an intrinsic expression of the core ISGs like ADAR, STAT1, STAT2, or CD47, which was confirmed with publicly available single-cell datasets." (PMID 39546567, 2024). "Treatment of PK-15 cells lacking Ifnar1 or Stat2 with IFNβ or poly (I:C) resulted in no inhibitory effects on viral infection by a lentiviral vector, influenza virus, and Akabane virus." (PMID 37939052, 2023). "Conversely, PK-15 Ifnar1 and PK-15 Stat2 k/o cells did not resist this viral infection, suggesting that cells lacking Ifnar1 or Stat2 cannot respond to IFNβ treatment." (PMID 37939052, 2023). "As expected, neither IFNAR1 (WT) nor IFNAR1 (W70C) in PK-15 Stat2 k/o cells showed restoration of the resistance to viral infection." (PMID 37939052, 2023). "The patients displayed various types of hyperinflammation, often triggered by viral infection or after LAV administration, which probably attested to unresolved viral infection in the absence of STAT2-dependent types I and III IFN immunity." (PMID 36976641, 2023). "Block of IFN signaling by mAb-IFNAR-antibody treatment, which was verified by lack of STAT2 phosphorylation, largely reverted this effect and facilitated virus infection, as reflected by higher levels of viral early and late proteins (lane 3)." (PMID 35319461, 2022). "Upon activation of ifn receptors by ligands, STAT1 and STAT2 are phosphorylated and form ISGF3 complex with IRF9, which is shuttled into the cell nucleus to trigger the expression of ISGs involved in immune response against viral infection." (PMID 35392096, 2022). "Likewise, STAT1 KO U3C cells, which also have low levels of STAT2, lack this positive feedback system and are unresponsive to IFN treatment and unable to protect against viral infection." (PMID 29892288, 2018). "The role of C6 in inhibiting the JAK-STAT pathway during virus infection may be masked to some degree by the effect of VH1 that dephosphorylates STAT1 and STAT2 rapidly after infection." (PMID 27907166, 2016). "As to the reasons for this elevated Ad replication, we have shown that the Type I IFN signal transduction pathway is not functional in STAT2 KO hamsters; these animals cannot up-regulate the expression of ISGs upon virus infection." (PMID 26291525, 2015). "To further dissect the response of monocytes to IFNα, we first monitored the phosphorylation of STAT1 and STAT2 in response to single or dual IFNα stimulation in the absence of viral infection." (PMID 20689596, 2010). "Our analysis found that Stat2 exhibited a high expression pattern after H1N1 infection in mice, which may be the transcriptional activation of related genes initiated by cellular pattern receptors in response to virus infection." (PMID 37228892, 2023). "STAT2 is frequently targeted for NS5-mediated IFN suppression in flaviviruses, and modification in NS5 nucleotide sequence could consequently impact host immune response and lead to more efficient viral infection." (PMID 37243180, 2023). "STAT2 is a member of the STAT family and plays an essential role in immune responses to extracellular and intracellular stimuli, including viral invasion: the gene product mediates host defence against viral infections through interferon (IFN)-α/β (IFNα/β) signalling." (PMID 36228008, 2022).
viral infection (continued). "Similarly, the STAT2 phosphorylation was not significantly changed at the early stage of viral infection compared with the luciferase-targeted control." (PMID 36148221, 2022). "The data suggest that early phosphorylation of STAT2 may be independent of JAKs during the viral infection." (PMID 36148221, 2022). "However, the occurrence of cases of hyperinflammation without convincing evidence of viral infection raises the possibility of a more complex defect of STAT2-dependent immunoregulation." (PMID 34448086, 2021). "By using this novel STAT2 KO hamster, the first non-murine rodent model of viral infection, we recently demonstrated that infection of pregnant hamsters leads to the vertical transmission of ZIKV to the uterus, placenta, and immune privileged sites, such as the testes and fetal brain." (PMID 30678320, 2019). "However, while this study also found that binding of NS5 to STAT2 is sufficient to prevent IFN signaling, STAT2 degradation is detected only when the N-terminus of NS5 is proteolytically processed, as it would be in the context of viral infection." (PMID 30558110, 2018). "Once again C6 associated with STAT2 and not STAT1, whilst N1 did not associate with either protein, confirming the specific interaction between STAT2 and C6 at endogenous protein levels during viral infection." (PMID 27907166, 2016). "Therefore, we determined whether early phosphorylation of STAT2 Y690 upon viral infection was independent of these IFNs." (PMID 36148221, 2022). "Intriguingly, we found that viral infection did not impact STAT1 and STAT2 expression and only slightly decreased IFN-I-mediated STAT phosphorylation." (PMID 33097660, 2020). "We did not explore the mechanisms behind the increased STAT2 level in GOF patients, but this is an important future research direction, especially given the difficulties with viral infections in STAT1 GOF disease." (PMID 31354696, 2019). "Moreover, the low number of CDV-infected cells expressing STAT1, STAT2 and MX indicates that the expression of these type I IFN pathway members is not directly induced by virus infection." (PMID 30939763, 2019). "Likewise, mice lacking STAT2 also exhibit similar phenotypes seen in STAT1KO mice, implying a pivotal role of STAT1 and/or STAT2 in response to viral infection." (PMID 19272190, 2009).
ZIKV infection (57 papers, 2017 to 2026). "Alternative models are stat-2-deficient guinea pig and hamsters, with certain range of advantages, however they cannot resemble many clinical aspects of ZIKV infection and they are relatively unexplored in therapeutic research, to the best of our knowledge." (PMID 34684182, 2021). "We recently reported that adult STAT2 KO hamsters are highly susceptible to ZIKV infection and that ZIKV RNA titers were detected in the testis, kidney, brain and spinal cord of infected STAT2 KO hamsters." (PMID 30678320, 2019). "In this study, we demonstrate that Stat2-/- mice are highly susceptible to ZIKV infection, recapitulate virus spread to the central nervous system (CNS), gonads and other visceral organs, and display neurological symptoms." (PMID 28278235, 2017). "In this study, we demonstrate for the first time that Stat2-/- mice are highly susceptible to ZIKV infection and recapitulate aspects of ZIKV pathogenesis and disease." (PMID 28278235, 2017). "In comparison Ifnar1-/- mice showed in general delayed disease symptoms and less body weight loss due to ZIKV infection than Stat2-/- mice." (PMID 28278235, 2017). "In comparison, Ifnar1-/- mice showed a delayed onset of disease, experienced less weight loss than Stat2-/- mice, displayed a wider range of neurological symptoms, and succumbed to ZIKV infection between day 7 to 8 post infection." (PMID 28278235, 2017). "Thus, human STAT2 knock-in (hSTAT2-KI) C57BL/6 mice have previously been used to enhance susceptibility to ZIKV infection." (PMID 40855992, 2025). "Indeed, we recently have demonstrated that STAT2 KO hamsters are highly susceptible to ZIKV infection." (PMID 30678320, 2019). "Similarly, a mouse strain deficient in both subunits of IFNAR as well as STAT2–/– mice were more susceptible to ZIKV infection and showed more severe ZIKV-associated pathology, compared to WT mice." (PMID 31652496, 2019). "In addition, it was demonstrated that ZIKV evades IFN-mediated host anti-viral defense by targeting signal transducer and activator of transcription 2 (STAT2), consistently, the STAT2-deficient mouse is vulnerable to ZIKV infection." (PMID 29361773, 2018). "To investigate whether elimination of STAT2 in mice was sufficient to render mice susceptible to ZIKV infection, we challenged Stat2-/- C57BL/6 mice with Uganda ZIKV (strain MR-766, 1947)." (PMID 28278235, 2017). "Indeed in our study, Stat2-/- mice were highly susceptible to ZIKV infection and disease." (PMID 28278235, 2017). "In this study, we adapted a model of maternal ZIKV infection in human STAT2 knock-in (hSTAT2) mice to investigate the effects of ZIKV infection during mid-gestation, aiming to mirror typical asymptomatic infections as they occur in humans." (PMID 41525323, 2026). "For instance, we have recently shown that STAT2 antagonism is a barrier to ZIKV infection of rodents." (PMID 41509424, 2025). "Replacement of human STAT2 CCD with mouse CCD prevented targeting of the chimeric STAT2 for degradation during ZIKV infection." (PMID 38675911, 2024). "The oncoprotein PIM1 kinase was revealed to inhibit the cellular type I IFN signaling pathway by vaguely regulating the phosphorylation of STAT1 or STAT2, which therefore promoted viral replication during ZIKV infection." (PMID 39679197, 2024). "ZIKV NS5—which degrades human STAT2—cannot degrade murine Stat2, potentially explaining why immunocompetent mice are resistant to ZIKV infection and disease induction." (PMID 39057782, 2024). "Signal transducer and activator of transcription 2 (STAT2) is a major driver of host restriction to ZIKV, and chicken STAT2 is distinct from human STAT2, potentially contributing to the observed resistance to ZIKV infection." (PMID 38675911, 2024). "Previous studies have reported that ZIKV infection induces the degradation of human STAT2 in a proteasome-dependent manner." (PMID 38018976, 2024).